CD4 (CD4 molecule)
Diseases named in the same sentence as CD4 in open-access papers (continued):
Sharing a sentence is not in itself a finding about the gene and the disease.
tumor (continued). "More importantly, traditional T cell therapy is often limited in effect due to exhaustion caused by the tumor microenvironment and poor antigen recognition, while CAR engineering enables CD4 + and CD8 + T cell subsets to work synergistically to completely eliminate tumors." (PMID 40604935, 2025). "Although they may not have as much direct effect, other immune cells such as B cells, DCs, macrophages, and CD4+ T-cells may have a significant pro-tumor and antitumor effect." (PMID 40098955, 2025). "Upon encountering tumor-associated antigens presented by MHC class II molecules on professional APCs, CD4+ T cells differentiate into specialized subsets—including Th1, Th2, Th17, Tfh, and Tregs —each with distinct transcriptional profiles, cytokine outputs, and functional consequences for the TME." (PMID 40660400, 2025). "The mechanism may involve the delivery of PD-L1 signals from granulomatous areas, inhibiting T cells and CD4+ T cells, and weakening anti-tumor immunity." (PMID 40061944, 2025). "The reduction of tumor growth with anti-VEGF was associated with increased infiltration of CD8+ effector T cells and CAR-T cells and reduced infiltration of immunosuppressive regulatory T cells (FOXP3+CD4+T cells)." (PMID 40894718, 2025). "On one hand, cytotoxic CD4+ T cells are characterized as cells expressing high levels of effector molecules and co-inhibitory molecules, such as programmed cell death protein 1 (PD-1), pointing to their tumor-suppressing functions." (PMID 41450739, 2025). "Additionally, CD73 was significantly upregulated in CD4+ and T regulatory cells of oligo-synchronous (BM simulantously with primary-tumor diagnosis) BM." (PMID 40346687, 2025). "Finally, to improve the prediction of postoperative recurrence in HCC patients following neoadjuvant immunotherapy, we integrated MVI, tumor capsule, and CD4+ T cell density of the CT region to construct a nomogram model." (PMID 41212769, 2025). "However, Th9 cells, a major subset of CD4+T cells, have been shown to produce high levels of IL-9 and exert anti-tumor effects in certain solid tumors such as breast cancer and lung cancer." (PMID 39958351, 2025). "Additionally, scRNA-seq data from HNSCC (GSE181919) defined the TME, encompassing tumor cells, CD4+ and CD8+ T cells, NK cells, B cells, plasma cells, macrophages, DCs, mast cells, fibroblasts, and endothelial cells." (PMID 40149859, 2025). "In a murine model of NASH-driven HCC, the removal of CD4+ T cells facilitated tumor progression." (PMID 40881277, 2025). "An increase of conventional CD4+ T cells and NK cells was observed at later timepoints (3.5% of conventional CD4 T cells at 200 mm3 vs 14.5% at 800 mm3, and 0.42% of NK cells at 200 mm3 vs 10% at 500 mm3), highlighting the impact of tumor burden in TME composition." (PMID 41041306, 2025). "The discovery of cytotoxic CD4+ T cells in BC and their role in response to PD-L1 inhibition is significant because it highlights a previously underappreciated aspect of immune-mediated tumor killing." (PMID 40177538, 2025). "In the tumour–adjacent bowel wall, T cell subsets including CD4+ Tcm, CD4+ Treg, CD8+ Tem and B cell subsets composed of memory B cell, naïve B cell and MAIT cells were significantly increased in the lamina propria, when naïve B cell and memory B cell were enriched in the muscularis propria." (PMID 39934971, 2025). "In contrast, tumor-infiltrating B (TIB) cells are located primarily in TLSs.B cells located in TLSs are linked to the response of antitumor antibodies and the proliferation of CD4+ T cell clones." (PMID 40406096, 2025). "TILs, mainly composed of CD8+ T cells, CD4+ T cells, Tregs, NK cells, and B cells, orchestrate complex immune responses through the secretion of cytokines that can either promote anti-tumor immunity or support tumor progression." (PMID 40868199, 2025).
tumor (continued). "In EwS, the CD8+T and Treg populations exhibit tumor-associated T-cell signatures, while CD4+T-cells resemble normal Th17 and naïve T-cell profiles, reflecting a complex immune landscape." (PMID 40242222, 2025). "Furthermore, treatment with all three doses resulted in comparable immuno-pharmacodynamic effects in the tumor, as evidenced by flow cytometric analysis of human CD4+ and CD8+ T cell infiltration." (PMID 41283511, 2025). "In addition, specific subsets of CD4+ T cells exert direct antitumoral cytotoxicity and induce tumor senescence." (PMID 40561008, 2025). "This suggests that the immune context of the tumor, including the balance of cytotoxic CD4+ T cells, may influence the effectiveness of immunotherapies." (PMID 40177538, 2025). "Correlation heatmap revealed that MCM4 expression was positively associated with tumor cells, while exhibiting a significant negative correlation with immune cells such as CD4+ T cells and CD8+ T cells." (PMID 40959096, 2025). "Finally, we co‐cultured CD4+ T cells with tumor cells for 48 h and found that the exogenous addition of CX3CL1 significantly promoted the secretion of IL10 and TGFβ." (PMID 39783838, 2025). "Immune infiltration analysis indicated that the abundance of CD4 T cells was significantly higher in both the tumor and precancerous lesion groups than in the control group, whereas no marked differences were observed in the abundance of CD8 T cells and B cells among the three groups." (PMID 40475759, 2025). "On one hand, this may result from NFE2L1 deficiency leading to ROS accumulation, which could activate dendritic cells (DCs) or enhance tumor antigen release, thereby promoting the recruitment and activation of CD4+ T cells and CD8+ T cells (marked by CD3e)." (PMID 40677211, 2025). "It has been demonstrated that blockade of the PD-1/PD-L1 axis causes reversal of the immunosuppressive phenotype, activates the adaptive immune system, triggers tumor antigen recognition, activates cytotoxic CD4+ and CD8+ T cells, and enhances antitumor efficacy." (PMID 40552154, 2025). "Interestingly, while CD4+ T cell depletion in calcipotriol-treated tumors reduced IL-24+ macrophages, it had no significant impact on the total number of macrophages in the tumor." (PMID 39782693, 2025). "Altogether, our results and the data already published suggest that CD4 + CD8 + phenotype should not be considered a hallmark of neoplasia in cats." (PMID 40822655, 2025). "Indeed, CD1C+ DCs have been correlated with the induction of anti-tumor T cell responses through production of activating cytokines and expression of co-stimulatory molecules that support the function of both CD4+ and CD8+ T cells." (PMID 40507267, 2025). "Interestingly, late-stage CD4+ T cell depletion after vaccination led to tumor shrinkage, suggesting that Tregs were the primary depleted subset." (PMID 40857404, 2025). "Finally, we conducted immune cell profiling with our scRNA-Seq results and identified that the CD4+ effector memory–like (EM-like) T cell is the only immune cell population that is substantially reduced in BAP1-KO tumor tissues." (PMID 39817454, 2025). "Furthermore, ROS-dependent endoplasmic reticulum stress in tumor cells suppresses DC surface calretinins exposure via autophagy, diminishing their maturation capacity and IL-6 secretion, thereby inhibiting CD4+/CD8+ T cell proliferation." (PMID 41246345, 2025). "Additionally, they observed that CD4+ T cells can upregulate the expression of chemokine receptors on cytotoxic T lymphocytes, which in turn facilitates their migration towards tumor cells and subsequent recognition, ultimately leading to their demise." (PMID 41230345, 2025). "Furthermore, a significant reduction in intratumoral CD4+Foxp3+ regulatory T cells (Tregs) was observed, suggesting that bardoxolone methyl disrupts immunosuppressive regulatory networks within the tumor microenvironment." (PMID 40732256, 2025).
tumor (continued). "Similarly, a reduction in CD4+CD25+ T cells was observed when DC2.4 cells were exposed to Py230 tumor antigens with ADMA treatment, while the CD8+CD25+ T cell population remained unchanged." (PMID 40429627, 2025). "Flow cytometry analysis on re-stimulated splenocytes, showed that mice treated with CBL0137 had significantly higher numbers of tumor-specific T cells, as shown by the higher percentages of T cells expressing IL-2, IFNγ or TNFα, particularly in the CD4+ T cell compartment." (PMID 39706891, 2025). "Remarkably, among the cell types that displayed a considerable decrease in Cluster B, most were involved in active anti-tumor responses, including activated CD4+ T cells, activated CD8+ T cells, activated B cells, natural killer cells, and activated dendritic cells." (PMID 41502516, 2025). "The lack of TREX1 in mouse models also resulted in increased immune activation in the tumor microenvironment, including immune infiltration and activation of CD4+ and CD8+ T cells, and NK cells, prevention of CD8+ T-cell exhaustion, and remodeling of the immunosuppressive myeloid compartment." (PMID 40581636, 2025). "Consistent with previous studies, pro-tumor immune cells such as M0 and M2 macrophages and CD4+ memory resting cells were relatively abundant, but effector T cells such as CD4+ T cells and CD8+ T cells were relatively rare, indicating a strong pro-tumor property and an immunosuppressive TME in PDAC." (PMID 40362181, 2025). "Additionally, CD4+ helper T (Th) cells exert influence on various immune cell subsets, with the Th1 and Th2 phenotypes playing dual roles in modulating anti-tumor immunity." (PMID 40830526, 2025). "Moreover, the glycolysis score was higher in CD4+ T cells originating from adjacent normal tissue compared to blood and it further increased in CD4+ T cells originating from the tumor." (PMID 40260243, 2025). "Importantly, membrane-bound antigens from tumor cells are internalized by B cells for potentiation of CD4 T cells." (PMID 40808959, 2025). "It is known that in OC CD14+ TAMs suppress the anti-tumor function of CD4+ T cells." (PMID 40872773, 2025). "The observation that exhausted or dysfunctional CD8+ and CD4+ T cells within tumors frequently express the B‐cell‐attracting chemokine CXCL13 suggests a programmed mechanism through which T cells recruit B‐cell support in response to persistent tumor antigens." (PMID 41235705, 2025). "While cytotoxic CD4+ tumor-infiltrating lymphocytes have anticancer activity in patients, whether these can be noninvasively monitored and how these are regulated remains obscure." (PMID 40299576, 2025). "Importantly, skin-derived TSLP, which can be induced by an FDA-approved topical medication, calcipotriol, can reach and activate CD4+ T cell–mediated antitumor immunity in the tumor microenvironment (TME)." (PMID 39782693, 2025). "CD4+ T cell depletion at early time points abrogated vaccine efficacy, whereas late depletion aided E743–77-pulsed mBMDC vaccine efficacy at later time points and enhanced tumor control and CD8+ T cell responses." (PMID 40857404, 2025). "Furthermore, CX3CL1 expressed by DCs promotes tumor infiltration of CD4+ and CD8+ T cells, correlating with improved prognosis." (PMID 41445742, 2025). "High levels of Treg cells may promote tumour growth by inhibiting the activity of CD4+ and CD8+T cells, which may contribute to the formation of VM." (PMID 39865437, 2025). "Interestingly, LAG-3 was predominantly co-expressed with TIM-3 on CD8+ TILs and was highly expressed on CD4+ T cells in both ascites and tumor tissues." (PMID 41315319, 2025). "Thus, an effective anti-tumor response requires robust activation of CD4+ and CD8+ T cells, while excessive Treg activity can dampen this response and promote tumor progression." (PMID 41007114, 2025). "Lacidipine also significantly inhibited tumor‐infiltrating CD4+CD25+Foxp3+ Tregs." (PMID 39585774, 2025).
tumor (continued). "We investigated the infiltration capacities of total CD8+ and CD4+ T-cells towards tumour region." (PMID 41310655, 2025). "Furthermore, we found that effector CD4+ T cells, particularly Tbet+ICOS+ Th1-like CD4+ T cells, were important for the remodeling of tumor vasculature and the increase of TA-HEVs during anti-CTLA-4 therapy in the MCAprog tumor model." (PMID 40460830, 2025). "Additionally, tumor tissues from WT-RM-1-HO-1-KO mice showed a similar enhancement in CD4+ T cells infiltration in the Doc-treated group compared to the control group (P < 0.05)." (PMID 40037158, 2025). "Recent literature also suggests that for those with HIV-associated EBV-SMT, improvement in CD4+ count can lead to a decrease in tumor size without surgery." (PMID 41281090, 2025). "In support of our hypothesis, deconvolution analyses revealed that tumours with high LEADR expression were enriched in CD4 T cells." (PMID 40461454, 2025). "Interestingly, tumour-derived Gal-1 increased frequency of CD4+CD25+Foxp3+ Treg cells in breast cancer, leading to an immunosuppressive TME." (PMID 39780187, 2025). "Additionally, LTS mice had 1.7-fold and 4.4-fold higher abundance of CD8 and CD4 T cells in their brain, respectively, compared to the “Tumor” mice." (PMID 40379691, 2025). "An adequate CD4+ Th cell polarization is essential for the appropriate coordination of cellular and humoral responses against pathogens or cancer cells, and each subset contributes differently to tumor progression." (PMID 41425582, 2025). "This unexpected finding suggests that in the context of established immune memory, CD4 + T cells may either acquire direct cytotoxic functionality or orchestrate anti-tumor responses through cell populations other than CD8 + T cells." (PMID 40585246, 2025). "Therefore, the activities of anti-CTLA-4 antibodies on tumor-infiltrating Tbet+ICOS+ Th1-like CD4+ T cells and tumor vasculature are both governed by antibody Fc effector function." (PMID 40460830, 2025). "Particularly, this group exhibits increased levels of infiltration by several types of immune cells, CD8+ T cells can directly kill tumor cells, while CD4+ T cells enhance the persistence of immune responses, and B cells are involved in antigen recognition and immunoglobulin production." (PMID 41019288, 2025). "The polarized state of macrophages may be associated with regulatory T cells (Tregs), potentially leading to tumor immune escape by hindering the function of CD4 T helper cells and the production of tumor-specific CD8 cytotoxic T lymphocytes (CTLs)." (PMID 40104395, 2025). "The increased expression of MHCII on GBM tumor cells and intratumoral immune cells post-M002 treatment may suggest that CD4+ T cells play a role in mediating the M002 therapeutic efficacy." (PMID 39885128, 2025). "Naïve CD4+ T cells co-cultured with irradiated mast cells exhibited a dose-dependent reduction in the proportion of Tregs, highlighting a potential shift toward an anti-tumor immune response." (PMID 40313959, 2025). "Additionally, in comparison to that in the tumor-bearing control group, the percentages of CD4+ Th1 cells in the CTT group were clearly elevated in the spleen and blood, and the percentage of splenic CD4+ Th2 cells was also increased." (PMID 40277945, 2025). "Thus, we further unraveled the role of CD4+ T cells engineered with the CD8-restricted PTPRZ11814-1822 TCR on tumor cell lysis in vitro through enriching CD4+ and CD8+ T cells via magnetic-activated cell sorting (MACS) post transduction." (PMID 39893177, 2025). "However, we observed a significant increase in tumor volume in CD4-depleted mice treated with CBD as compared to CBD-treated wild-type mice suggesting the importance of CD4+T cells in CBD-mediated anti-tumor activity." (PMID 40475776, 2025). "Additionally, DBI exhibited a weak positive correlation with activated CD8+ T cells and activated CD4+ T cells, both of which are critical for anti-tumor immunity." (PMID 40426943, 2025).
tumor (continued). "Selective depletion of interleukin-10-expressing (IL-10+) Treg cells promoted tumor growth by lifting the restraint on IL-17 production from effector CD4+ T cells, thereby directly stimulating tumor cell proliferation; depletion of IL-10- Treg cells led to pronounced tumor regression." (PMID 41401810, 2025). "Additionally, in an in vivo mouse xenograft model, LINC00892 overexpression suppressed tumor growth and metastasis, accompanied by enhanced immune cell infiltration such as CD4+ and CD8+ T cells." (PMID 40308809, 2025). "Similarly, we detect increased IFN-γ, TNF-α, and IL-2 expression in CD4+ T cells after coculture with RCOR2-KO tumor cells." (PMID 40608411, 2025). "EGFR is expressed not only in tumor cells but also in CD4+ T lymphocytes." (PMID 40502915, 2025). "Interestingly, both tumor‐derived CD4+ and CD8+ T cells produce considerably more TNF‐α and IFN‐γ than those in the PB." (PMID 40498413, 2025). "CD4+ T cells, or helper T cells, support anti-tumor immunity by coordinating immune responses." (PMID 39911388, 2025). "Simultaneously, mice treated with HMP1G NPs showed the most effective suppression of Treg cell populations (CD3+CD4+Foxp3+) both in the spleen and within the tumor, whereas 1‐MT and HMPG NPs treatments only slightly inhibited Treg cell populations within the tumor." (PMID 39661740, 2025). "To further evaluate the predictive efficacy, we utilized ROC curve analysis, and compared the performance of the nomogram model with three independent indicators (MVI, tumor capsule, and CD4+ T cell density of the CT region) at 6, 12, and 18 months postoperative." (PMID 41212769, 2025). "In addition, nano micelles further reprogrammed the immunosuppressive TME by promoting the infiltration of CD8+ and CD4+ into tumor lesions." (PMID 40486836, 2025). "In particular, CD8+ TILs tend to exhibit a dominant phenotype that varies significantly across tumors, whereas CD4+ TILs show a more uniform phenotype across patients, perhaps reflecting distinct responses to the metabolic selection pressures within the tumor milieu." (PMID 40523956, 2025). "Thus, tumor regressions have been observed in patients with advanced cancers following treatment with exclusively CD4 + T cells or HLA-class II restricted TCR." (PMID 41410746, 2025). "In young mice, tumor volume significantly increased following depletion of CD4+ or CD8+ T cells." (PMID 41332581, 2025). "Notably, mice treated with the gE71-90 MHC-II-restricted minimal peptide epitope with polyI:C also controlled growth of the primary tumor which suggests a contribution of CD4+ T cells to the antitumor response." (PMID 40280970, 2025). "In addition to directly eliminating tumor cells through cytotoxicity, CD4+ T cells have been reported to enhance the function of other immune populations by modulating the TME." (PMID 40759573, 2025). "The enhancement of cellular immunity in the 4T1 tumor model is also explained by other studies, in which tumor progression was associated with an increase in CD8+ Gzmb cells, CD8/CD4 equilibrium, and IFN-γ+ CD4 cells." (PMID 39877637, 2025). "Innovations such as ligand-functionalized nanoparticles, pH-responsive carriers, and biomimetic nanocarriers further enhance the ability to selectively modulate immune responses within the tumour microenvironment, thereby potentiating CD4+ T-cell activation and function." (PMID 40860882, 2025). "In the TC-TLS, the effective scores of CD8+LAG-3−PD-1−TIM-3− T cells (surrounding cells: CD8+LAG-3−PD-1+TIM-3−), CD8+PD-1−TIM-3+ T cells (surrounding cells: CD8+PD-1−TIM-3−), and CD4+FoxP3+ T cells (surrounding cells: CD4+FoxP3−) were notably higher than those in the tumour and the stroma." (PMID 39901202, 2025). "Importantly, these findings confirm prior genetic data that suggest ALDH1A3 suppresses anti-tumor CD4 T cells." (PMID 41210994, 2025).